DUX4 (double homeobox 4)
Diseases named in the same sentence as DUX4 in open-access papers (continued):
Sharing a sentence is not in itself a finding about the gene and the disease.
cancer (continued). "Notably, others have characterized an induced dependence on POLE in CCNE/CDK2 activated cancers, thus indicating that CIC::DUX4 may operate through a similar molecular pathway." (PMID 40760094, 2025). "We therefore reasoned that the IGH-DUX4 translocation on the repressive haplotype would avoid high-level DUX4 expression if it were transcribed from the haplotype with an active Eμ which would not be tolerated in normal or cancer cells." (PMID 31243274, 2019). "Another possibility that was not addressed in the present study is that DUX4 expression might influence metastatic potential of cancer cells via CXCR4-SDF1 axis." (PMID 27556182, 2016). "DUX4 expression in several cancer cell lines was sufficient to prevent the induction of MHC-I expression in response to interferon gamma (IFNγ); however, it was unclear whether this represented an activity restricted to MHC-I or a broader activity of DUX4 in regulating protein expression." (PMID 37747887, 2023).
tumor (46 papers, 2009 to 2026). "DUX4 expression in advanced cancers is associated with signatures of host anti-tumor immunity inhibition." (PMID 38829686, 2024). "This is interesting given that DUX4 can suppress MHC class I expression in several malignancies in a manner associated with tumour immunotherapy resistance." (PMID 37856562, 2024). "We determined that DUX4 expression was associated with a significant decrease in PD-L1 levels on both tumor and host immune cells, consistent with DUX4-induced suppression of IFN-γ signaling." (PMID 38829686, 2024). "DUX4 expression is a significant predictor of survival even after accounting for tumor mutational burden and other molecular and clinical features in this cohort, with DUX4 expression associated with a median reduction in survival of over 1 year." (PMID 38829686, 2024). "DUX4 expression is a significant predictor of survival even after accounting for tumor mutational burden and other molecular and clinical features in this cohort, with DUX4 expression associated with a median reduction in survival of over one year." (PMID 37502871, 2023). "We identified 8 relapse-specific lncRNAs associated with metabolic pathways in the DUX4 subtype overlapping with lncRNAs reported to synergistically dysregulate metabolic pathways in multiple tumor contexts." (PMID 30642353, 2019). "Three additional TFs (SMARCA1, DUX4, and CDX1) were identified as potential direct or indirect targets of the HPV genome and were significantly associated with tumor progression in mammalian systems." (PMID 41012596, 2025). "Mechanistically, POLE loss increases DNA damage and induces p21-mediated cellular senescence to limit CIC::DUX4 tumor growth in vitro and tumor formation in vivo." (PMID 40760094, 2025). "Using immunohistochemistry and proteomic approaches, two independent studies recently identified increased CCNE1 protein expression in patient-derived CIC::DUX4 tumor specimens, thus demonstrating the potential translational impact of our findings." (PMID 40760094, 2025). "Collectively, we credential POLE as a CIC::DUX4 target and further characterize a functional network through which CIC::DUX4 operates to drive tumor progression and survival." (PMID 40760094, 2025). "Collectively, these findings suggest that CIC::DUX4 co-opts native cellular machinery to enhance tumor cell growth and survival." (PMID 40760094, 2025). "These animal models provide a powerful opportunity to study CIC::DUX4 core circuitry during tumor initiation and in established tumors." (PMID 38916046, 2024). "They demonstrated that a iP300w, a potent p300/CBP inhibitor, reversed CIC::DUX4 associated histone H3 acetylation marks and consequently suppressed CIC::DUX4 transcriptional activity while limiting tumor growth." (PMID 38882060, 2024). "We similarly examined the correlation of DUX4 expression status with PD-L1 levels in the tumor and immune compartments quantified via IHC." (PMID 38829686, 2024). "Sanger sequencing of the explanted tumor identified an in-frame CIC::DUX4 transcript fusing CIC exon 20 to exon 1 of DUX4 with a junction nucleotide sequence 5′-GGGTGGAG-3′." (PMID 38882060, 2024). "Recent work from our group and others showed that DUX4 is expressed in a small subset of primary tumors, where it suppresses tumor cell antigen presentation and response to IFN-γ signaling." (PMID 38829686, 2024). "Our results reveal how fusing the C-terminal portion of DUX4 to the N-terminus of CIC converted a well-established tumor suppressor into a powerful oncogene." (PMID 38275898, 2024). "We performed differential gene expression analyses on the individuals stratified according to tumor DUX4 expression status." (PMID 38829686, 2024). "(B) Bayesian information criterion (BIC) measurements for goodness of fit for the full (tumor mutational burden [TMB], Clinical, DUX4 expression) vs. reduced Cox PH models, where lower values indicate better fit." (PMID 38829686, 2024).
tumor (continued). "(G) PD-L1 expression on tumor cells stratified by DUX4 expression status measured by immunohistochemistry in the original study." (PMID 38829686, 2024). "The reason for that difference in tumor prognosis is most likely that DUX4 expression and MHC-I downregulation renders tumors less susceptible to treatment with checkpoint inhibitors." (PMID 37876935, 2023). "Understanding the contribution of aberrant DUX4 expression to different tumor types requires additional studies." (PMID 34943834, 2021). "This rearrangement most commonly connects CIC (19q13) to DUX4 (4q35 or 10q26); some tumours harbour CIC rearrangements with non-DUX4 partner genes, including FOXO4, LEUTX, NUTM1, and NUTM2A1,3–8." (PMID 31676869, 2019). "The distribution of some DUX-related transcripts in normal and tumor cervical tissues was analyzed by RT-PCR with DUX4-specific primers." (PMID 19473516, 2009). "The CIC::DUX4 fusion oncoprotein retains CIC DNA-binding specificity and converts the repressor activity associated with wild-type CIC to a potent transcriptional activator that drives tumor progression and chemoresistance." (PMID 40760094, 2025). "Recently, DUX4 and MUC5AC were introduced as helpful diagnostic stains; the latter is reported to be typically expressed in scattered tumor cells and—despite its low specificity—may be particularly useful given its wide availability." (PMID 40722508, 2025). "Correspondingly, therapeutic strategies targeting DUX4-mediated pathways are multifaceted, and targeting the pathways activated by DUX4 could disrupt these embryonic programs, potentially hindering tumor growth and dissemination." (PMID 40427614, 2025). "DUX4 reactivation is associated with immune evasion mechanisms, notably the suppression of MHC class I expression, which impairs antigen presentation and facilitates tumor escape from immune surveillance." (PMID 40427614, 2025). "This is interesting given the enrichment of adaptive immunity pathways in genes differentially expressed between control and FSHD PBMCs, particularly considering a report connecting DUX4 expression in tumours to suppression of both MHC-I and MHC-II related gene expression." (PMID 37856562, 2024). "The authors speculate that the CIC::DUX4 fusion is a highly potent oncogene (similar to Kras) that leads to spontaneous tumor formation." (PMID 38882060, 2024). "Thus, an improved understanding of endogenous CIC::DUX4 dosage and how it impacts tumor cell survival and death can enhance our understanding of fusion oncoprotein stability and expression." (PMID 39530749, 2024). "Moreover, inhibition of CBP and p300 suppressed CIC::DUX4-driven transcription and xenograft tumor growth." (PMID 38916046, 2024). "Screening for DUX4 tumor expression, with binarized results such as through IHC using anti-DUX4 antibodies, could have clinical utility." (PMID 38829686, 2024). "Preclinical studies identified CIC::DUX4 to molecularly depend on cell cycle mediators CCNE1 and WEE1 with CCNE1 being established as a direct transcriptional target of CIC::DUX4 that drives tumor growth and survival through an acquired dependence on CCNE/CDK2 complex." (PMID 38882060, 2024). "Our study shows an analogous mechanism in CDS, where the fusion of the DNA binding domain of CIC to the transactivation domain of DUX4 converts a transcriptional repressor into a powerful activator, concomitantly turning a well-established tumor suppressor into a potent oncogene." (PMID 38275898, 2024). "Interestingly, the bulk tumour RNA‐seq deconvolution algorithm TIMER revealed a lower proportion of CD8+ T and natural killer cells in DUX4‐expressing tumours, in line with evasion of tumour immune surveillance." (PMID 34151531, 2021). "It is likely that DUX4 might be an initial trigger of a cascade of transcription factors regulating protooncogenes, tumor suppressors, and proapoptotic genes." (PMID 19473516, 2009).
tumor (continued). "Subsequently, DUX4 activates a shared set of genes, including ZSCAN4, TRIM, PRAMEF, and retrotransposon-associated elements, which are expressed in both early embryos and tumor cells, thereby inducing a metastable, totipotent-like state and enhancing immune evasion and cellular plasticity." (PMID 40427614, 2025). "Mechanistically, DUX4 suppresses MHC-I expression through multiple mechanisms, thereby promoting immune evasion in tumor cells." (PMID 40427614, 2025). "Tumor samples were examined histologically, and RNA sequencing was performed to confirm the presence of the CIC::DUX4 fusion." (PMID 41053525, 2025). "Although DUX4 expression induces a metastable early embryonic stem cell program and suppresses antigen presentation, contributing to immune evasion, targeting the epigenetic regulators involved in this reprogramming may be possible to reverse the immunosuppressive tumor microenvironment." (PMID 40427614, 2025). "CRISPR knockout of etv4 significantly suppressed tumor formation, suggesting that ETV4 has a cooperative role in CIC::DUX4 tumorigenesis." (PMID 38916046, 2024). "As we consistently observed intermediate activity of the C1-deleted CIC::DUX4 compared with full-length CIC::DUX4 across several in vitro assays, we next aimed to test the impact on tumor growth in vivo." (PMID 39530749, 2024). "Despite the DUX4-mediated suppression of MHC class I, therapies aimed at enhancing antigen presentation or modulating the tumor microenvironment to promote immune cell infiltration could mitigate DUX4-induced immune suppression." (PMID 40427614, 2025). "DUX4 expression in advanced-stage solid cancers correlates with reduced expression of chemokines and MHC class 1 genes, and inhibition of T cell recruitment to tumour sites." (PMID 40940582, 2025). "Given the major changes in H3K27ac signals observed in CIC-DUX4-depleted cells, and the reported interaction between the C-terminus of wt DUX4 and the chromatin remodeler p300, we next focused on the possible interaction between these two proteins in the context of CDS tumor cells." (PMID 38275898, 2024). "We directly assessed the correlation of DUX4 expression to immune cell exclusion by examining CD8+ T cell abundance in the tumor microenvironment, measured by immunohistochemistry (IHC) on formalin-fixed paraffin-embedded patient tumor sections." (PMID 38829686, 2024). "Gene activation by CIC::DUX4 requires CBP and/or p300, as drug inhibition of CBP and p300 reverses the regulatory circuitry of the disease, alters the expression of oncogenic pathways and reduces xenograft tumor burden." (PMID 38916046, 2024). "We confirmed a tumor-maintaining potency of the MLL-AF4 fusion protein in PDX models in vivo and used the technique to identify DDIT4L as therapeutic targets in PDX ALL carrying the recently described DUX4-IGH translocation." (PMID 34580292, 2021). "Intriguingly, while there is correlation between DUX4 expression and permissive 4qA haplotypes in tumours, it is not absolute." (PMID 34151531, 2021). "Western blot analysis of explanted tissue could not reliably detect CIC::DUX4 protein expression in any tumor sample but did reveal increased ETV5 levels in full-length CIC::DUX4 tumors compared with EV or dC1 tissue." (PMID 39530749, 2024).
myopathy (23 papers, 2011 to 2025). A disease of the muscle in which the muscle fibers do not function properly. "Here, we used the DUX4 IMEP mouse model, in which a DUX4 expression plasmid is injected and electroporated into a TA muscle, inducing dose-dependent local myopathy." (PMID 38542301, 2024). "Dr. Wallace reported several in vivo studies in both the uninduced and tamoxifen-induced TIC-DUX4 mouse models, which recapitulate mild and more severe forms of DUX4-related myopathy, respectively." (PMID 35039091, 2022). "We have recently created a line of conditional DUX4 transgenic mice, FLExDUX4, that develop a myopathy upon induction of human DUX4-fl expression in skeletal muscle." (PMID 32278354, 2020). "DUX4 activates a number of germline genes, immune mediators, apoptosis pathways, and alters RNA and protein metabolism, leading to progressive myopathy." (PMID 32759720, 2020). "Previously we generated a conditional DUX4-fl expressing transgenic mouse, FLExD, and showed that high expression of DUX4-fl in skeletal muscle can produce a very severe myopathy with some FSHD-like pathology." (PMID 32278354, 2020). "This would result in high levels of DUX4-fl expression from each recombined myonucleus, thus generating a DUX4-mediated FSHD-like myopathy." (PMID 29415061, 2018). "In order to generate a model suitable for investigating DUX4-induced myopathy, it was necessary to induce DUX4-fl expression levels using cre-mediated recombination." (PMID 29415061, 2018). "Efforts to model DUX4 myopathy in mice have foundered either in being too severe, or in lacking muscle phenotypes." (PMID 28916757, 2017). "As we found that Ret was activated by DUX4 in murine satellite cells, it becomes a potential candidate for contributing to DUX4-induced myopathy." (PMID 27841748, 2016). "FSHD is a myopathy, and DUX4-fl expression is induced in differentiated myogenic cells; thus, the use of these cells, as opposed to the lymphocytes used in most other studies, allowed analysis of epigenetic status and pathogenic gene expression in the most affected cell type." (PMID 25904990, 2015). "Our study opens new perspectives about DUX4 involvement in FSHD, i.e. how such a rare protein could cause damages leading to a myopathy." (PMID 23206257, 2013). "Other animal model work includes a mouse carrying human D4Z4 repeats, which showed some evidence of sporadic DUX4 expression but no myopathy, and adeno-associated viral (AAV) vector-mediated delivery of DUX4 to zebrafish and mouse skeletal muscle, which showed profound myopathy." (PMID 28754837, 2017). "In this model, a DUX4 expression plasmid (pCIneo-DUX4) is injected into the mouse Tibialis Anterior (TA) hindlimb muscle followed by electroporation (IMEP), leading to local DUX4 expression and myopathy." (PMID 38542301, 2024).
infection (9 papers, 2013 to 2025). The state of being infected such as from the introduction of a foreign agent such as serum, vaccine, antigenic substance or organism. "Infection of DUX4 ko 293T cells resulted in an almost complete loss of most HSV-1 genes tested in Western Blot, like ICP0, ICP4, ICP27 and VP16 compared to wt 293T cells, confirming that DUX4 is critical for HSV-1 replication." (PMID 39814710, 2025). "We show that herpesviruses from all human subfamilies, papillomaviruses as well as Merkel cell polyomavirus induce a robust expression of DUX4 upon infection in vitro and in vivo." (PMID 39814710, 2025). "Since high levels of DUX4 cause considerable cell death, we used a low multiplicity of infection to limit DUX4 expression." (PMID 40634301, 2025). "Expression of two DUX4-specific mini-TRIMAway constructs prevents spread of HSV-1 replication in a low MOI infection setting with a GFP-expressing HSV-1 compared to a control mini-TRIMaway construct as shown by immunofluorescence and flow cytometry." (PMID 39814710, 2025). "ICP0 and ICP4 induce expression of DUX4 at early stages of infection for a brief period, indicated by 4sU-labelling of RNAs." (PMID 39814710, 2025). "DUX4 mRNA expression was also induced upon infection of primary human melanocytes with HSV-1, emphasizing the physiological relevance of DUX4 induction." (PMID 39814710, 2025). "DUX4 can either stay in the ‘infected’ cell until it dies or diffuse to another cell to spread the ‘infection’." (PMID 37184373, 2023). "To elucidate the involvement of HSV-1 tegument proteins in the induction of DUX4 expression we performed infection experiments with HSV-1 mutants depleted of the immediate early proteins ICP0, ICP4 and gamma-34.5." (PMID 38168299, 2023). "ICP0 and ICP4 induce expression of DUX4 at early stages of infection for a brief period, indicated by nuclear staining of DUX4 in ICP4+/VP26− cells." (PMID 38168299, 2023). "Even after infection with UV-inactivated virus, DUX4 protein was still induced, indicating that incoming components of the virion contribute to DUX4 induction." (PMID 38168299, 2023). "We used a recombinant HSV-1 expressing ICP4-YFP and VP26-RFP in order to visualize progression of infection and localization of DUX4." (PMID 38168299, 2023). "In our model, DUX4 can be seen as an ‘infectious agent’, and expression of DUX4 target genes can be seen as the ‘infection’, which leads to cell death." (PMID 37184373, 2023). "We show that herpesviruses from all human subfamilies as well as Papillomaviruses induce a robust expression of DUX4 upon lytic infection." (PMID 38168299, 2023). "Nascent RNA-Seq analysis identified that only a slight fraction of genes not expressed in uninfected fibroblasts are transcriptionally upregulated in infection, outside of DUX4 genes and those upregulated by type I and II interferons." (PMID 34578417, 2021). "We could show that wildtype (wt) HSV-1 infection as well as infection with HSV-1-Δ γ34.5 resulted in DUX4 protein expression, whereas DUX4 expression is abrogated in cells infected with HSV-1 lacking either ICP0 (expressing ICP4-YFP protein) or ICP4." (PMID 39814710, 2025). "We could show that wildtype (wt) HSV-1 infection as well as infection with HSV-1-Δ γ34.5 resulted in DUX4 expression, whereas DUX4 expression is abrogated in cells infected with HSV-1 lacking either ICP0 or ICP4." (PMID 38168299, 2023). "However, using CUT&Tag and CUT&RUN we could detect direct binding of DUX4 to the genome of HSV-1 GFP (F-strain) starting at about 4 h post infection." (PMID 39814710, 2025). "However, using CUT&Tag we could detect direct binding of DUX4 to the HSV-1 genome at about 4h post infection." (PMID 38168299, 2023). "Analysis of the kinetics of DUX4 expression upon HSV-1 infection further demonstrated that DUX4 protein could be detected as early as 4h post infection with protein levels constantly increasing over the course of infection." (PMID 38168299, 2023).